CCNB1IP1 (cyclin B1 interacting protein 1)
Description:
Ubiquitin E3 ligase that acts as a limiting factor for crossing-over during meiosis: required during zygonema to limit the colocalization of RNF212 with MutS-gamma-associated recombination sites and thereby establish early differentiation of crossover and non-crossover sites. Later, it is directed by MutL-gamma to stably accumulate at designated crossover sites. Probably promotes the dissociation of RNF212 and MutS-gamma to allow the progression of recombination and the implementation of the final steps of crossing over (By similarity). Modulates cyclin-B levels and participates in the regulation of cell cycle progression through the G2 phase. Overexpression causes delayed entry into mitosis.
Synonyms: C14orf18; HEI10
Tractability: PROTAC: UniProt records ubiquitination sites on it; ubiquitination databases record sites on it.
Gene: Protein-coding gene on chromosome 14 (20,311,353 to 20,333,314, reverse strand). Ensembl gene ENSG00000100814.
Subcellular location: Nucleus; Chromosome
Gene Ontology:
Molecular function: identical protein binding; protein binding; ubiquitin protein ligase activity
Biological process: chiasma assembly; reciprocal meiotic recombination; protein ubiquitination
Cellular component: synaptonemal complex; chromosome; condensed nuclear chromosome; nucleus
Genetic constraint (gnomAD): Loss-of-function variants: 12 observed, 25.7 expected, observed/expected ratio (o/e) 0.47, 90% interval 0.3 to 0.76. The upper end of that interval is the gene's LOEUF score, 0.76, which puts it in group 3 of 6, group 1 being the genes least tolerant of losing a copy. Missense variants: 275 observed, 354.8 expected, observed/expected ratio (o/e) 0.78, 90% interval 0.7 to 0.86. Synonymous variants: 119 observed, 121.3 expected, observed/expected ratio (o/e) 0.98, 90% interval 0.85 to 1.14.
Cancer hallmarks: invasion and metastasis (suppresses)
Homologues: Orthologues: chimpanzee CCNB1IP1 (99% identical), macaque CCNB1IP1 (99% identical), dog CCNB1IP1 (96% identical), rabbit CCNB1IP1 (94% identical), guinea pig CCNB1IP1 (94% identical), pig CCNB1IP1 (93% identical), rat Ccnb1ip1 (89% identical), mouse Ccnb1ip1 (88% identical), tropical clawed frog ccnb1ip1 (71% identical), zebrafish CCNB1IP1 (49% identical).
Diseases named in the same sentence as CCNB1IP1 in open-access papers:
CCNB1IP1 is named in the same sentence as 17 diseases in open-access papers, as found by Europe PMC text mining. Sharing a sentence is not in itself a finding about the gene and the disease. The quoted sentences say what the papers report.
breast carcinoma (3 papers, 2015 to 2023). "Studies have confirmed that CCNB1IP1 is under‐expressed in colon cancer, breast cancer and non‐small cell lung cancer." (PMID 37461251, 2023). "The human CCNB1IP1 protein has been reported to interact with merlin, a tumor suppressor protein, and the expression levels of the CCNB1IP1 gene have been found to be altered in cancers such as uterine leiomyoma, melanoma, and breast cancer." (PMID 26110280, 2015). "A large-scale in-situ hybridization study on cancerous tissues showed that CCNB1IP1 was underexpressed in breast cancer and most likely non-small cell lung cancer." (PMID 26110280, 2015).
lung carcinoma (2 papers, 2014 to 2023). "The alterations of the CCNB1IP1 ubiquitin ligases correlated significantly with breast and lung cancer prognostic factors, especially in lung cancer." (PMID 36696967, 2023).
Uterine leiomyoma (2 papers, 2015 to 2017). The presence of a leiomyoma of the uterus. "In uterine leiomyomas, HMGA2 fusion transcripts were reported with various sequences including COX6C (8q22.2), ALDH2 (12q24.12), CCNB1IP1 (14q11.2), RAD51B (14q24.1), and RTVL-H 3_ LTR (21q21.2)." (PMID 28591699, 2017).
glioblastoma (1 paper, 2021). The most malignant astrocytic tumor (WHO grade IV). "A prognostic model of glioblastoma was constructed based on SUMOylation regulator-related molecules (ATF7IP, CCNB1IP1, and LBH)." (PMID 33898460, 2021). "Finally, a prognostic model of glioblastoma was constructed based on SUMOylation regulator-related molecules (ATF7IP, CCNB1IP1, and LBH)." (PMID 33898460, 2021).
hepatoma (1 paper, 2025). "Taken together, these findings suggest that AdipoR1 reduces cyclin B1 expression through the E3 ubiquitin ligase CCNB1IP1 in hepatoma cells." (PMID 39849382, 2025).
intestinal cancer (1 paper, 2021). "It was shown that the sep15 gene silencing in CT-26 intestinal cancer cells led to an increase in the expression of the ccnb1ip1 gene, which encodes a protein that functions as ubiquitin ligase and is able to interact with cyclin B, promoting its degradation." (PMID 34360564, 2021).
cancer (10 papers, 2014 to 2025). A tumor composed of atypical neoplastic, often pleomorphic cells that invade other tissues. "Our results further demonstrated the ability of CCNB1IP1 to ubiquitinate cyclin B1, thus targeting the E3 ubiquitin ligase involved in cell cycle regulation is expected to provide new therapeutic strategies for cancer therapy." (PMID 39849382, 2025). "Importantly, we identified a series of ZnO NPs-responsive genes, including TLNRD1 and CCNB1IP1, that promote cancer cell death under ZnO NPs treatment." (PMID 34620733, 2021). "CCNB1IP1, CCNC, CCND2, CDK5R2, CDK9, and GAK were upregulated in all three cancer regions." (PMID 33302383, 2020).
tumour (8 papers, 2008 to 2023). "Increasing evidence demonstrated that the proliferative deficiencies and transcriptional deregulation of CCNB1IP1 caused tumour mutations and invasion." (PMID 36696967, 2023). "The Ccnb1ip1 gene encodes an ubiquitin E3 ligase, which functions in the progression of the cell cycle through G2/M and is considered to be involved in tumor development." (PMID 26110280, 2015). "CCNB1IP1 was initially identified as an interacting protein of cyclin B1 involved in regulating cell cycle progression, and may be implicated in tumour events." (PMID 37461251, 2023). "MTT, EdU incorporation, colony and tumour sphere formation assays, and a mouse xenograft tumour model were utilized to examine the biological function of CCNB1IP1." (PMID 37461251, 2023). "ShCCNB1IP1‐IMR‐32 cells re‐expressing the CCNB1IP1 M4 mutant showed significant tumour growth inhibition compared to cells re‐expressing CCNB1IP1 WT." (PMID 37461251, 2023). "The colony and tumour sphere formation ability of MYCN‐AM NB cells re‐expressed M4 mutant was significantly diminished compared to those transfected with CCNB1IP1 WT." (PMID 37461251, 2023). "To further clarify the effect of CCNB1IP1 on MYCN‐AM NB cell tumour growth, we constructed Ctrl‐, shMYCN‐ and shMYCN+CCNB1IP‐IMR‐32 cells‐derived subcutaneous xenograft tumour models." (PMID 37461251, 2023). "Presently, studies on the expression and biological functions of CCNB1IP1 in tumours, especially in NB, are still relatively unexplored." (PMID 37461251, 2023). "CCNB1IP1 was upregulated in MYCN‐amplified (MYCN‐AM) NB cell lines and patients‐derived tumour tissues, which was associated with poor prognosis." (PMID 37461251, 2023). "Our finding also provides plausibility for predicting the risk of tumour progression and provides additional insight for drug development and refinement of individualized treatment regimens for high‐risk NB based on MYCN and CCNB1IP1 protein interactions." (PMID 37461251, 2023). "Therefore, understanding epigenetic mechanisms that control the transcription of Parp2 and Ccnb1ip1 helps gain further insights into their functional roles in meiosis, mitosis, and tumor development." (PMID 26110280, 2015). "Therefore, further characterization of the insulator and enhancer in the Ccnb1ip1 locus may help understand the roles of CCNB1IP1 in cell cycle regulation and tumor development." (PMID 26110280, 2015). "Focally deleted regions identified the tumour-suppressor genes RHOA at 3p21, CDKN2A and CDKN2B at 9p21, RAD51B, MAX, DICER1, BCL11B, NKX2-1, CCNB1IP1 and BAZ1A at 9q33." (PMID 34980126, 2022). "The genes CCNB1IP1, CUL7 and E2F2 are involved in cell cycle control and cell growth and have expression levels in our study that promotes cell growth in the tumours from deceased patients." (PMID 18778486, 2008). "Xenografts in the shMYCN group were significantly reduced in size, weight and growth rate compared with the Ctrl group, whereas tumour suppression was not alleviated in the shMYCN+CCNB1IP1 group, even with the rescue of CCNB1IP1 expression." (PMID 37461251, 2023). "Based on the high expression of CCNB1IP1 in MYCN‐AM NB cells, we hypothesized that an excess of CCNB1IP1 facilitated MYCN‐driven tumour‐promoting functions of NB cells." (PMID 37461251, 2023). "In addition, IHC results confirmed that CCNB1IP1 immunostaining was attenuated in the MYCN knockdown group and rescued in the CCNB1IP1 overexpression group in tumour tissues." (PMID 37461251, 2023). "Although inhibition of CCNB1IP1 alone could not fundamentally eliminate tumour cells, it greatly delayed and inhibited tumour proliferation and growth in vitro and in vivo." (PMID 37461251, 2023). "However, consistent with the tumour growth phenotype, restoration of CCNB1IP1 expression did not effectively reverse tumour proliferation suppression caused by MYCN silencing, as evidenced by the unchanged Ki67 staining intensity in the shMYCN+CCNB1IP1OE group versus the shMYCN group." (PMID 37461251, 2023).
CCNB1IP1 also shares sentences with these, for which no sentence is quoted: melanoma (2 papers); cervical cancer (1); gastric cancer (1); hypopharyngeal cancer (1); Infertility (1); lung adenocarcinoma (1); neuroblastoma (1); Sepsis (1); uterine cancer (1).